SERPINB7 (serpin family B member 7)
Description:
Might function as an inhibitor of Lys-specific proteases. Might influence the maturation of megakaryocytes via its action as a serpin.
Synonyms: MEGSIN; PPKN; TP55
Tractability: PROTAC: ubiquitination databases record sites on it.
Gene: Protein-coding gene on chromosome 18 (63,752,935 to 63,805,376, forward strand). Ensembl gene ENSG00000166396.
Subcellular location: Cytoplasm
Subcellular location (Human Protein Atlas): Endoplasmic reticulum; Mitochondria
Gene Ontology:
Molecular function: serine-type endopeptidase inhibitor activity
Biological process: positive regulation of collagen biosynthetic process; positive regulation of glomerular mesangial cell proliferation; positive regulation of platelet-derived growth factor production; positive regulation of transforming growth factor beta1 production
Cellular component: cytoplasm
Genetic constraint (gnomAD): Loss-of-function variants: 13 observed, 19.7 expected, observed/expected ratio (o/e) 0.66, 90% interval 0.43 to 1.05. The upper end of that interval is the gene's LOEUF score, 1.05, which puts it in group 4 of 6, group 1 being the genes least tolerant of losing a copy. Missense variants: 365 observed, 337.56 expected, observed/expected ratio (o/e) 1.08, 90% interval 0.99 to 1.18. Synonymous variants: 121 observed, 125.41 expected, observed/expected ratio (o/e) 0.96, 90% interval 0.83 to 1.12.
Homologues: Orthologues: chimpanzee SERPINB7 (100% identical), macaque SERPINB7 (95% identical), dog SERPINB7 (83% identical), rabbit SERPINB7 (81% identical), pig SERPINB7 (76% identical), mouse Serpinb7 (74% identical), rat Serpinb7 (74% identical). Paralogues in human: SERPINB11 (43% identical), SERPINB3 (41% identical), SERPINB4 (41% identical), SERPINB12 (40% identical), SERPINB1 (39% identical), SERPINB13 (39% identical), SERPINB6 (38% identical), SERPINB2 (37% identical), SERPINB8 (37% identical), SERPINB9 (36% identical), SERPINB10 (34% identical), SERPINC1 (33% identical), and 24 more.
Diseases named in the same sentence as SERPINB7 in open-access papers:
SERPINB7 is named in the same sentence as 39 diseases in open-access papers, as found by Europe PMC text mining. Sharing a sentence is not in itself a finding about the gene and the disease. The quoted sentences say what the papers report.
Nagashima-type palmoplantar keratoderma (4 papers, 2021 to 2026). "Nagashima-type palmoplantar keratoderma (NPPK) is an autosomal recessive disorder caused by biallelic loss-of-function variants in the SERPINB7 gene, whereas Hashimoto's thyroiditis (HT) is a common autoimmune endocrine disease." (PMID 42206102, 2026). "In addition, CD36 associated with platelet glycoprotein IV deficiency and SERPINB7 associated with Nagashima-type palmoplantar keratoderma have been unreported in China, and their prevalence is unclear." (PMID 36072675, 2022). "Nagashima-type palmoplantar keratoderma is an autosomal recessive PPK, and c.796C>T (p.Arg266∗) in SERPINB7 is the most common disease-causing variant in the Asian population." (PMID 34616427, 2021). "In contrast, the lesions in Nagashima-type PPK are not progressive, and the pathogenic gene is usually to be SERPINB7." (PMID 37393290, 2023). "Nagashima-type palmoplantar keratoderma (NPPK) is characterized by non-progressive, diffuse, and cross-gradient hyperkeratosis caused by mutations in the SERPINB7 gene on chromosome 18q21.33." (PMID 34616427, 2021).
psoriasis (4 papers, 2012 to 2024). An autoimmune condition characterized by red, well-delineated plaques with silvery scales that are usually on the extensor surfaces and scalp. "SerpinB7 deficiency affects the skin barrier function and the expression of inflammatory mediators in mice, and exacerbates psoriasis-like lesions." (PMID 35864103, 2022). "SerpinB7 is identified as a skin-specific endogenous protease inhibitor, but the role and underlying mechanism in psoriasis are poorly understood." (PMID 35864103, 2022). "In summary, this study found that SerpinB7, a gene specifically expressed by keratinocytes, was associated with the occurrence and development of psoriasis, through transcriptomic screening and identification." (PMID 35864103, 2022). "SerpinB7 deficiency can cause epidermal barrier dysfunction in IMQ-induced psoriasis like models." (PMID 39737188, 2024). "Therefore, our data imply that the SerpinB7 deficiency exacerbates psoriasis, leading to increased levels of inflammatory factors and dysregulated epidermal differentiation." (PMID 35864103, 2022). "The expression of SerpinB7 in psoriasis is controversial, which requires further studies to confirm." (PMID 39737188, 2024). "SerpinB7 knockdown in HaCaT cells drastically increased the expression of psoriasis-related chemokines (CCL20, CCL27, CXCL1, CXCL2) and antimicrobial peptides LL37 and S100A8 in the M5-stimulated in vitro psoriatic model." (PMID 35864103, 2022). "Our finding that stimulation of keratinocytes with M5 induces inflammation that aptly recapitulates the features of psoriasis as in vitro psoriatic model showed that SerpinB7 expression increased with the severity of the psoriatic lesion." (PMID 35864103, 2022). "Consistently, immunoblot and immunofluorescent staining showed that the SerpinB7 was abundantly increased in lesion skin of psoriasis patients compared to healthy control, specifically localized to epidermal keratinocytes." (PMID 35864103, 2022). "In this study, we have characterized SerpinB7 as a new psoriatic candidate gene and found a significant positive correlation between the expression of SerpinB7 and psoriasis severity." (PMID 35864103, 2022). "Our findings first described the critical role of SerpinB7 in the regulation of keratinocyte differentiation and psoriatic microenvironment mediated via keratinocytes' intracellular calcium flux, proposing a new candidate for therapeutic targets in psoriasis." (PMID 35864103, 2022). "It was found that SerpinB7 was positively correlated with the severity of psoriasis." (PMID 35864103, 2022). "In this study, we investigated the correlation between the expression of SerpinB7 and psoriasis, and determined whether it has potential functional relevance in psoriasis." (PMID 35864103, 2022). "In addition, genes involved in epidermal differentiation, including IVL, TGM, SPRR2A/B/E/G, SERPINB7/8, are induced in DM (red bar), which have also been shown to be elevated in other inflammatory skin diseases, such as psoriasis and atopic dermatitis." (PMID 22235269, 2012). "This study explored the relationship between SerpinB7 and psoriasis, analyzes the mechanism of regulating psoriasis keratinocytes, and provides new ideas for further understanding of the skin homeostasis regulatory network and the occurrence and development of psoriasis." (PMID 35864103, 2022). "However, the role of SerpinB7 in skin homeostasis and psoriasis pathophysiology remains unknown." (PMID 35864103, 2022). "To explore the potential role of SerpinB7 in psoriasis, we subjected SerpinB7-/- mice to IMQ-induced psoriatic model, which exhibited a significant increase in the mouse Psoriasis Area and Severity Index (PASI), evaluates erythema, scales, and thickness compared to those of SerpinB7+/+ mice." (PMID 35864103, 2022). "Whether SerpinB7 has a positive or negative effect on the pathogenesis of psoriasis depends on its expression level, which needs to be further verified." (PMID 39737188, 2024).
psoriasis (continued). "Compared to healthy people and non-lesion skin of psoriasis patients, patients with psoriasis had significantly increased SerpinB7 mRNA in lesional skin, and a positive correlation between the expression of psoriasis severity marker IL-17 and SerpinB7." (PMID 35864103, 2022).
atopic dermatitis (3 papers, 2012 to 2025). "Subsequently, a GWAS study using a cohort from Finland, Estonia, and the UK identified an SNP (rs188720898) located near SERPINB7 as a modulator of susceptibility for atopic dermatitis and found the association of the SNP with the Finnish NPPK founder variant in high linkage disequilibrium." (PMID 39749860, 2025). "This phenotype is widely found in a range of eczematous conditions and would suggest that common mutations affecting SERPINB7 expression could partially explain the missing heritability in atopic dermatitis GWAS." (PMID 33836063, 2021). "Furthermore, a pathological variant of SERPINB7 was identified as a risk factor for the development of atopic dermatitis in a genome‐wide association study (GWAS) of atopic dermatitis, indicating that the frequent co‐occurrence of NPPK and atopic dermatitis is not a mere coincidence." (PMID 39749860, 2025). "As an example, we present SERPINB7 as a new putative candidate gene in atopic dermatitis GWAS due to not only a phenotypic match between its target Mendelian disease and eczema but also due to colocalization evidence in the skin." (PMID 33836063, 2021).
cervical cancer (3 papers, 2022 to 2025). A primary or metastatic malignant neoplasm involving the cervix. "High expression of serine protease inhibitor 7 (SERPINB7) is associated with unfavorable overall survival of patients with cervical cancer, as well as patients with pancreatic cancer and NSCLC patients receiving a standard care, including chemotherapy." (PMID 41469472, 2025). "The results showed that PLCB4, FBLN5, TSPAN8, CST6, and SERPINB7 were highly expressed in cervical cancer tissues (p<0.05)." (PMID 36408178, 2022).
Hyperkeratosis (3 papers, 2021 to 2025). Hyperkeratosis is a histopathological term defining a thickened stratum corneum and may be present in many different skin conditions, with many possible overlaps. "Crucially, SERPINB7’s expression is elevated in the epidermis, and nonsense mutations in the gene cause Nagashima-Type Palmoplantar Keratosis, characterized by well-demarcated diffuse hyperkeratosis with redness on palms and feet." (PMID 33836063, 2021).
bladder cancer (2 papers, 2023 to 2024). "Compared with normal bladder samples, the protein expression of PLOD1, ATP6V1B1, HSD17B1, SERPINB7, and PYCR1 in bladder cancer tissues was upregulated, while EGR1 in cancer tissues was down-regulated." (PMID 37880682, 2023).
breast carcinoma (2 papers, 2017 to 2019). "Lastly, SERPINB7 is a peptidase that is well known to be upregulated in patients with breast cancer and lung cancer." (PMID 31404090, 2019).
diffuse PPK (1 paper, 2025). "A genetic diagnosis was found in a comparable percentage in patients with diffuse PPK, despite the presence of founder variants in SERPINB7 and AQP5 in the Finnish patients." (PMID 39630431, 2025).
Palmoplantar keratoderma (1 paper, 2025). Abnormal thickening of the skin of the palms of the hands and the soles of the feet. "Approximately 10 years have elapsed since NPPK was demonstrated to be an independent genetic disease, and the most prevalent palmoplantar keratoderma (PPK) in East Asian countries due to a high prevalence of founder mutations in SERPINB7." (PMID 39749860, 2025).
cancer (5 papers, 2013 to 2025). A tumor composed of atypical neoplastic, often pleomorphic cells that invade other tissues. "Moreover, DSG1, C6orf15, SOST, SPRR2A, SERPINB7, MYBPH, and KRT1 were considerably expressed in the high-risk group, indicating their potential roles as cancer-promoting genes in the development of BLCA." (PMID 37664033, 2023). "Four genes (SERPINB7, INHBA, GJA1, and NID1) have two isoforms that have significantly different expression between the cancer and non-oncogenic groups." (PMID 23594586, 2013).
tumor (2 papers, 2022 to 2023). "For example, expression of transcripts encoding the tumor promoters Serpinb7, Aqp5, and Cd68 was induced by Src and suppressed by contact normalization." (PMID 35177067, 2022). "All SERPINB families are associated with tumor cell invasion, with SERPINB1, SERPINB5 and SERPINB7 being more strongly associated with invasion." (PMID 37064125, 2023).
bacterial infection (1 paper, 2024). "Upregulation of GJB2, VNN1, DUSP4, SerpinB7, and IL10, and downregulation of PKMYT1, S100A4, GGTA1P, and SLC22A31 were most strongly associated with bacterial infection." (PMID 39395995, 2024).
SERPINB7 also shares sentences with these, for which no sentence is quoted: food allergy (2 papers); palmoplantar keratosis (2); pancreatic cancer (2); asthma (1); autosomal recessive disease (1); carnitine deficiency (1); chronic pancreatitis (1); clear cell renal cell carcinoma (1); Crigler-Najjar syndrome (1); eczema (1); Erythema (1); genetic disease (1); Hashimoto thyroiditis (1); head and neck squamous cell carcinoma (1); IgA nephropathy (1); Immunodeficiency (1); inflammatory skin disease (1); leukemia (1); lung adenocarcinoma (1); lung carcinoma (1); lung squamous cell carcinoma (1); melanoma (1); pancreatic ductal adenocarcinoma (1); phenylketonuria (1); prostate carcinoma (1); sitosterolemia (1); uterine corpus endometrial carcinoma (1).